CENPF (centromere protein F)
Description:
Required for kinetochore function and chromosome segregation in mitosis. Required for kinetochore localization of dynein, LIS1, NDE1 and NDEL1. Regulates recycling of the plasma membrane by acting as a link between recycling vesicles and the microtubule network though its association with STX4 and SNAP25. Acts as a potential inhibitor of pocket protein-mediated cellular processes during development by regulating the activity of RB proteins during cell division and proliferation. May play a regulatory or permissive role in the normal embryonic cardiomyocyte cell cycle and in promoting continued mitosis in transformed, abnormally dividing neonatal cardiomyocytes. Interaction with RB directs embryonic stem cells toward a cardiac lineage. Involved in the regulation of DNA synthesis and hence cell cycle progression, via its C-terminus. Has a potential role regulating skeletal myogenesis and in cell differentiation in embryogenesis. Involved in dendritic cell regulation of T-cell immunity against chlamydia.
Synonyms: hcp-1; CENF; CILD31; PRO1779; STROMS
Tractability: PROTAC: ubiquitination databases record sites on it.
Gene: Protein-coding gene on chromosome 1 (214,603,172 to 214,664,574, forward strand). Ensembl gene ENSG00000117724.
Subcellular location: Cytoplasm, perinuclear region; Nucleus matrix; Chromosome, centromere, kinetochore; Cytoplasm, cytoskeleton, spindle
Subcellular location (Human Protein Atlas): Nucleoplasm
Pathways (Reactome):
Cell Cycle: Amplification of signal from unattached kinetochores via a MAD2 inhibitory signal; EML4 and NUDC in mitotic spindle formation; Mitotic Prometaphase; Polo-like kinase mediated events; Resolution of Sister Chromatid Cohesion; Separation of Sister Chromatids
Signal Transduction: RHO GTPases Activate Formins
Gene Ontology:
Molecular function: DNA-binding transcription factor binding; dynein complex binding; protein binding; protein homodimerization activity; chromatin binding; microtubule binding
Biological process: chromosome segregation; kidney development; metaphase chromosome alignment; mitotic cell cycle; negative regulation of DNA-templated transcription; protein transport; regulation of G2/M transition of mitotic cell cycle; ventricular system development; kinetochore assembly; mitotic spindle assembly checkpoint signaling; response to xenobiotic stimulus
Cellular component: chromosome, centromeric region; ciliary transition fiber; cytoplasm; kinetochore; midbody; nuclear envelope; nuclear matrix; nucleoplasm; nucleus; outer kinetochore; spindle; spindle pole; chromatin; cytosol; axoneme; centrosome; ciliary basal body; perinuclear region of cytoplasm; pronucleus
Genetic constraint (gnomAD): Loss-of-function variants: 193 observed, 296.11 expected, observed/expected ratio (o/e) 0.65, 90% interval 0.58 to 0.73. The upper end of that interval is the gene's LOEUF score, 0.73, which puts it in group 3 of 6, group 1 being the genes least tolerant of losing a copy. Missense variants: 3,298 observed, 3,524.2 expected, observed/expected ratio (o/e) 0.94, 90% interval 0.91 to 0.96. Synonymous variants: 1,231 observed, 1,301.5 expected, observed/expected ratio (o/e) 0.95, 90% interval 0.9 to 0.99.
Homologues: Orthologues: chimpanzee CENPF (99% identical), macaque CENPF (95% identical), pig CENPF (76% identical), dog CENPF (75% identical), guinea pig CENPF (66% identical), rat Cenpf (65% identical), mouse Cenpf (64% identical), tropical clawed frog cenpf (31% identical), zebrafish cenpf (26% identical), zebrafish si:dkeyp-115e12.6 (11% identical).
Diseases named in the same sentence as CENPF in open-access papers:
CENPF is named in the same sentence as 110 diseases in open-access papers, as found by Europe PMC text mining. Sharing a sentence is not in itself a finding about the gene and the disease. The quoted sentences say what the papers report.
breast cancer (64 papers, 2008 to 2025). A primary or metastatic malignant neoplasm involving the breast. "Gene CENPF is a cell cycle-associated gene, and it has been identified as a marker of cell proliferation in breast cancers." (PMID 38741183, 2024). "High expression of both CENPE and CENPF was associated with low oestrogen and progesterone receptor expression levels in breast cancer." (PMID 37592220, 2023). "Overexpression of CENPF in breast cancer was associated with poor prognosis and tumor bone metastases by controlling parathyroid hormone-related peptide (PTHrP) production via activating PI3K-AKT-mTORC1." (PMID 35354488, 2022). "ABL1, a non-receptor tyrosine kinase, has been implicated in response to DNA-damaging chemotherapeutics in tissue culture, while high expression of the centrosomal protein CENPF has been associated with good chemoresponses in breast cancers." (PMID 32734521, 2020). "It has been reported that the overexpression of CENPF associated with poor prognosis in hepatocellular carcinoma, breast cancer, colorectal gastrointestinal stromal tumors, esophageal squamous cell carcinoma and prostate cancer." (PMID 28449718, 2017). "Here we review the current literature on centromere protein F, its association with breast cancer and present the first case of this antibody being identified in a person with a BRCA1 gene mutation." (PMID 26868636, 2016). "A gene that may play an important role in breast cancer progression is CENPF, which encodes centromere protein F and is overexpressed in this type of cancer." (PMID 40563399, 2025). "CENPF is closely associated with cell proliferation and is upregulated in multiple cancers, such as nasopharyngeal cancer, hepatocellular carcinoma, esophageal squamous cell carcinoma, gastrointestinal stromal tumors and breast cancer 23-25." (PMID 33531976, 2021). "However, CENPF was reported to be overexpressed, drive tumorigenesis and/or associated with poor prognosis in several human malignancies, including breast cancer, prostate cancer, bladder cancer, gastric cancer, hepatocellular carcinoma, pancreatic carcinoma." (PMID 33023625, 2020). "CENPF may serve as a novel therapeutic, diagnostic, and/or prognostic target in breast cancer treatment." (PMID 31632198, 2019). "Remarkably, proteins prominently expressed in NmFMC compared with other groups, such as F13A1, CENPF, INSR, SCAF1 and PDK1, have been implicated in human breast cancer, further supporting the potential use of FMC as a model for studying human breast cancer." (PMID 38951817, 2024). "The published data from the TCGA showed that CENPF expression in breast cancer tissues was significantly higher than that in adjacent peritumoral tissues (n = 1 376, P < 0.05)." (PMID 36720923, 2023). "Kaplan‒Meier plotter data showed that high CENPF expression portended worse recurrence-free survival in breast cancer patients receiving neoadjuvant chemotherapy (NACT) (n = 403, log-rank P = 0.035)." (PMID 36720923, 2023). "Previous studies have found that CENPF, MELK, PBK, TOP2A and NEK2 are upregulated in breast cancer and this is associated with a poor prognosis." (PMID 36776306, 2023). "This unbiased approach allowed us to identify a panel of five biomarkers, DNMT3B, EXO1, MCM10, CENPF and CENPE, that are robustly and significantly associated with disease-free survival prognosis in breast cancer." (PMID 37592220, 2023). "Highly expressed CENPF was observed in various human malignant tumors, such as GC, prostate cancer, breast cancer and hepatocellular cancer." (PMID 35346060, 2022). "Cyclin B1, cyclin A, and CENPF were overexpressed in several tumor types including esophageal carcinoma, bladder urothelial carcinoma, breast cancer, and colon adenocarcinoma." (PMID 35484963, 2022). "The typical examples are the positive relevance of CENPF overexpression to malignancy and bad prognosis of prostate cancer, as well as bone metastasis in breast cancer." (PMID 35346060, 2022).
breast cancer (continued). "High expression of CENPF has been observed in various cancers, such as prostate cancer and breast cancer." (PMID 35627287, 2022). "Overexpression of CENPF has been reported to have poor prognosis and metastasis of breast cancer, lung adenocarcinoma and prostate cancer." (PMID 36260870, 2022). "In terms of the mechanism, it has been found that CENPF plays a role in breast cancer through activation of the PI3K-AKT-mTORC1 pathway." (PMID 36644760, 2022). "MCM3AP-AS1 is highly expressed in breast cancer cells and promotes tumor growth by targeting centromere protein F (CENPF)." (PMID 35783010, 2022). "Several evidences suggest that enhanced CENPF is a reliable prognostic indicator of poor survival for breast cancer, prostate cancer, and hepatocellular carcinoma." (PMID 35627287, 2022). "It has been reported that CENPF is related to multiple kinds of malignancies such as prostate and breast cancer." (PMID 34603487, 2021). "CENPF was further shown to activate the PI3K/AKT/mTORC1 axis to upregulate the expression of PTHrP in breast cancer cells." (PMID 34064589, 2021). "The CENPF gene is also amplified in other solid tumors including hepatocellular and breast cancers and correlates with patients’ outcomes." (PMID 33828156, 2021). "The expression of centromere protein F (CENPF) as a marker of cell proliferation was revealed to be higher in bone metastases of breast cancer compared to the primary tumor or metastases to other organs." (PMID 34064589, 2021). "The result showed that U50A consistently downregulates SMC5, ATRX, CENPE, and CENPF, indicating a widespread phenomenon that these genes are downstream targets of U50A in breast cancer." (PMID 34944924, 2021). "A study consists of 295 breast cancer patients demonstrated that overall survival obviously correlated with the upregulation of CENPF." (PMID 34925510, 2021). "CENPF has also been reported as a prognostic factor for breast cancer, renal cancer, and bladder cancer." (PMID 33154194, 2020). "Studies have demonstrated that breast cancer patients with high expression of CENPF in tumor tissue are more prone to bone metastasis." (PMID 33148251, 2020). "Using the ONCOMINE database, we compared the expression of CENPF in breast cancer and normal tissues." (PMID 31632198, 2019). "Previously studies have demonstrated CENPF as both a prognostic and predictive gene in breast cancer." (PMID 25312014, 2014). "Ueda and coworkers found that CENPF was upregulated in tumors with a high proliferation rate in breast cancer." (PMID 24489730, 2014). "While the breast cancer candidacy of CENPF, KIF14, NEK2, DTL, CKS1B, ASPM and EXO1 genes have been identified earlier, there is only one prominent report indicating the candidacy of EXO1 in breast cancers and remains to be investigated." (PMID 24147022, 2013). "The subsequent filtering with the combined p-value <0.005 across 6 datasets, yielded 7 candidate genes ASPM, KIF14, NEK2, DTL, CENPF, CKS1B and EXO1 that are significantly associated with poor clinical outcome of the breast cancer patients." (PMID 24147022, 2013). "Further, a SNP in CENPF gene (R2943G; rs438034) that occurs in the SAIF genome is associated with a poor breast cancer survival." (PMID 22938532, 2012). "In a study of breast cancer which showed a prognostic value of mitosin, the same CENPF antibody in equivalent dilution was used." (PMID 20398247, 2010). "Moreover, we identified several hub genes associated with type II pRCC progression, including CENPF, which has been implicated as a prognostic biomarker in RCC, breast cancer, and bladder cancer." (PMID 41405963, 2025). "Survival prognostic analysis using the Kaplan‒Meier Plotter tool showed that low levels of CENPF expression predicted better overall survival (n = 1 879, log-rank P = 1.3e − 07) and recurrence-free survival (n = 4929, log-rank P < 1e − 15) in breast cancer." (PMID 36720923, 2023).
breast cancer (continued). "CENPF has been found to be overexpressed in various malignant tumours, such as prostate cancer, breast cancer, and nasopharyngeal carcinoma, and to activate signalling pathways related to malignant tumour progression to promote the proliferation and metastasis of cancer cells." (PMID 36720923, 2023). "Haiting Xu pointed out suppressing effects of miR-383-5/CENPF axis in breast cancer." (PMID 35346060, 2022). "For example, miR-28-5p attenuates breast cancer progression via targeting CENPF." (PMID 35346060, 2022). "CENPF overexpressed was correlates with poor prognosis and tumor bone metastasis in breast cancer." (PMID 33390818, 2021). "Moreover, CENPF also promotes breast cancer progression and bone metastasis by activating the AKT/mTOR signaling pathway." (PMID 35141213, 2021). "A number of studies have reported that CENPF expression is overexpressed in several human malignancies including breast cancer, hepatocellular carcinoma, nasopharyngeal cancer, gastrointestinal stromal tumors, esophageal squamous cell carcinoma, and non-Hodgkin’s lymphoma." (PMID 32973403, 2020). "CENPF promotes breast cancer bone metastasis by activating PI3K-AKT-mTORC1 signaling." (PMID 32973403, 2020). "However, in ER+/PR+/HER2- breast cancer, because of the significant suppression for centromere protein F (CENPF)-mediated transcriptional activation of CHK1 induced by ADR itself, CHK1 inhibition fails to sensitize ADR toxicity." (PMID 32210727, 2020). "However, in ER+/PR+/HER2- breast cancer, the CENPF-mediated transcriptional activation for CHK1 is suppressed by ADR itself." (PMID 32210727, 2020). "Based on a study elucidating the tumor biology of increasing SUV such as MYC-overexpression or centromere protein F-expression, breast cancer with high SUV levels could indicate aggressive tumors." (PMID 30407916, 2019). "Restoring the tumor suppressor function of HIC-1 gene may partially derive benefit from reduced CENPF expression on breast cancer cells." (PMID 24489730, 2014). "They proposed that CENPF was a prognostic indicator for primary breast cancer." (PMID 24489730, 2014). "In addition, the high expression of CENPF may eventually induce bone metastasis of breast cancer cells." (PMID 35627287, 2022). "In addition, there may be a close correlation between CENPF and PTHrP in breast cancer bone metastasis." (PMID 31632198, 2019). "The role of CENPF in breast cancer (BC) bone metastasis remains unclear." (PMID 31632198, 2019). "Commonality with most of the short-listed genes (CENPF, KIF14, NEK2, CKS1B and ASPM) is their positive association with proliferation marker Ki-67, thereby, indicating their possible role in cell cycle related dysregulations and the resultant proliferation of breast cancer cells." (PMID 24147022, 2013). "LINC00536 has been demonstrated to enhance the development and progression of breast cancer through the miR-214/ROCK1 axis and the miR-4282/CENPF axis." (PMID 38279317, 2024). "For instance, F13A1 was prominently expressed in human estrogen receptor-negative breast cancer, while targeting CENPF resulted in tumor growth inhibition in human breast cancer." (PMID 38951817, 2024). "Additionally, CENPE, TOP2A, CENPF, TTK, and NDC80 are highly expressed in the cell cycle of basal-like breast cancer." (PMID 35496042, 2022). "In this analysis, expression of 2 genes (CENPF, PLXNA1) showed significant differences between groups that died from breast cancer (n = 388) vs alive/lost to follow up (n = 962) (p < 0.05), and significantly predicted differences in length of survival in Kaplan–Meier analyses (p < 0.05)." (PMID 32734521, 2020).
breast cancer (continued). "In recent years, shreds of evidence have arisen that the overexpression of CENPF was a frequent behavior in different malignant tumors and was closely related to the tumor deterioration and dismal prognosis in multiple neoplasms, including HCC, breast cancer, prostate cancer and other tumors." (PMID 35123514, 2022). "Overexpression of CENPF may correlate with poor prognosis in breast cancer, CENPF may be a new prognostic biomarker in nonmuscle invasive bladder cancer, and the HnRNPR-CCNB1/CENPF axis contributes to gastric cancer proliferation and metastasis." (PMID 32040444, 2020). "For instance, CENPF (Centrosome protein F) and NEK2 (NIMA (never in mitosis gene a) - related kinase 2) were reported for their association with poor prognosis and chromosomal instability in breast cancer." (PMID 24147022, 2013). "These analyses revealed five genes, DNMT3B, EXO1, MCM10, CENPF and CENPE, that are normally not expressed in healthy breast tissue but become frequently activated in breast cancers." (PMID 37592220, 2023).